ABCC5 (ATP binding cassette subfamily C member 5)
Diseases named in the same sentence as ABCC5 in open-access papers (continued):
Sharing a sentence is not in itself a finding about the gene and the disease.
liver (1 paper, 2023). "The use of PBA in IR injury affected the levels of the ABC transporter genes (Abcc2, Abcc5, and Abcg2), significantly suppressed inflammation and oxidative stress, reduced ER stress, and thus significantly mitigated liver IR injury." (PMID 38168520, 2023).
ABCC5 also shares sentences with these, for which no sentence is quoted: melanoma (2 papers); Obesity (2); primary angle-closure glaucoma (2); small cell lung carcinoma (2); acute myeloid leukemia (1); anaemia (1); asthma (1); astrocytic tumor (1); chronic myelogenous leukemia (1); chronic pancreatitis (1); dengue fever (1); Dubin-Johnson syndrome (1); epilepsy (1); head and neck cancer (1); head and neck squamous cell carcinoma (1); hearing loss (1); lung adenocarcinoma (1); lung disease (1); malignant glioma (1); metastatic cancers (1); metastatic melanoma (1); neuroblastoma (1); osteoarthritis (1); pancreatic ductal adenocarcinoma (1); papillary carcinoma (1); pneumococcal infection (1); retinoblastoma (1); Stargardt disease (1); triple-negative breast carcinoma (1); uveal melanoma (1).